CPT2 (carnitine palmitoyltransferase 2)
Diseases named in the same sentence as CPT2 in open-access papers (continued):
Sharing a sentence is not in itself a finding about the gene and the disease.
cancer (continued). "Furthermore, they observed that expression of CPT1B and CPT2 was generally higher in the cancer cells, raising the possibility that increased CPT expression levels may contribute to perhexiline sensitivity." (PMID 37110858, 2023). "Therefore, further studies on CPT2 may provide new insights into the development of effective cancer immunotherapy." (PMID 37251324, 2023). "Patients with CRC may have a better prognosis if CPT2 is expressed highly in their cancer tissues." (PMID 37205121, 2023). "Similarly, using IHC, we found that CPT2 expression was increased in G1 carcinomas." (PMID 34679988, 2021). "However, much less is known about the role of CPT2 in cancer." (PMID 28977850, 2017). "In comparison to CPT1, relatively less studies have pointed out the roles of CPT2 and CACT in cancer." (PMID 29996946, 2018). "Multiple malignant tumors are characterized by the significant overexpression of FAO enzymes Carnitine Palmitoyltransferase 1A (CPT1A), Carnitine Palmitoyltransferase 1B (CPT1B), and Carnitine Palmitoyltransferase-2 (CPT2)." (PMID 41164182, 2025). "In this context, targeting enzymes like CROT, CRAT, CPT2, CPT1, and CAC, which regulate lipid transport and utilization, may inhibit cancer cell growth by disrupting their metabolic flexibility." (PMID 40001519, 2025). "Notably, the expression of ECI2, MCCC2, SUCLG2, and CPT2 was higher and that of OXCT1 was lower in cancer tissues than in para‐cancer tissues." (PMID 39491527, 2024). "Interestingly, many mitochondria-associated ELIdn genes were downregulated in fibroblasts with metastatic transition of cancer, including COX10, MSTO1, CPT2, and MDH1B." (PMID 35565326, 2022). "Firstly, we did not provide direct in vivo evidence for cancer-promoting effects of the CPT2 down-regulation." (PMID 36195841, 2022). "Our current data also reveal a potential crosstalk between CPT1A/CPT2-mediated lipid metabolism and ERK1/2-controlled cell proliferation, implicating a cooperative network of mitochondrial FAO in response to radiation in resistant cancer cells." (PMID 31803610, 2019). "Both the log-rank test and the univariate Cox regression analysis confirmed that lower expression of CPT2, ACAA2 and ACADM in cancer tissues could predict poor prognosis of CRC patients." (PMID 28977850, 2017). "Decrease of CPT2 leads to upregulation of SCD1 and enhanced lipogenesis in HCC cells, indicating that CPT2 may be a key regulator in SCD1-mediated lipid metabolism in drug resistant cancer cells." (PMID 35646898, 2022). "Thus, the CPT1A/CPT2-mediated FAO activity may be differently regulated in normal and cancer cells, which warrants further studies." (PMID 31803610, 2019).
metabolic disorders (18 papers, 2012 to 2025). "Fatty acid disorders, such as CPT2 deficiency, that disrupt lipid utilization are one type of metabolic disease." (PMID 39199302, 2024). "Carnitine palmitoyltransferase II (CPT2) deficiency is a metabolic disorder that prevents the body from effectively using long-chain fatty acids (LCFAs) for energy." (PMID 39850164, 2024). "We and others propose that zebrafish can be used to investigate metabolic disease, such as CPT2 deficiency, and the association with neurodevelopmental and neurodegenerative disorders in humans." (PMID 39199302, 2024). "Mutations in the genes encoding CPT1 and CPT2 can lead to rare and often severe metabolic disorders." (PMID 39473663, 2024). "Our results suggest that nutritional compensation with short chain fatty acid such as acetate may ameliorate metabolic disorders caused by CPT2 deficiency." (PMID 40065099, 2025). "CPT2 deficiency is a rare metabolic disorder manifesting across a spectrum of phenotypes." (PMID 39473663, 2024). "CPT2 mutations have been reported to cause several metabolic disorders including general muscle damage, temperature changes, infections, disturbances of Na+/K+ ATPases, neuroleptic syndrome, excessive use of muscular force, and conditions related to lipid metabolism increases." (PMID 25781464, 2015). "CPT2 knockdown studies suggest that the zebrafish model system will be useful for continued studies investigating how metabolic disorders influence gene expression and protein function at early stages of brain development and contribute to neurodegenerative disease states later in life." (PMID 39199302, 2024).
myopathy (18 papers, 2007 to 2025). A disease of the muscle in which the muscle fibers do not function properly. "In this case, after finding a myopathic pattern on histopathology, WES was reanalyzed with a dedicated myopathy panel discovering a CPT2 variant and leading to the diagnosis of carnitine palmitoyl-transferase II deficiency stress-induced myopathy." (PMID 35572607, 2022). "Two phenotypes are associated with the extremely reduced CPT2 activity in genetically deficient patients: neonatal lethality or, in milder forms, myopathy." (PMID 29271911, 2017). "Instead, a lower dose (5 mg rosuvastatin) was used in view of the known history of CPT2 deficiency and the propensity of any underlying myopathy to be aggravated by statin therapy." (PMID 23326270, 2012). "Heterozygous CPT2 variants can cause adult-onset stress-induced myopathy (OMIM #255110)." (PMID 35572607, 2022). "The roles of other select myopathy genes (CPT2, RYR1, CACNA1S) are covered in more detail in the relevant sections below." (PMID 31861911, 2019). "Two patients were found to have metabolic forms of myopathy one due to defects in the muscle glycogen phosphorylase encoding gene (PYGM) and the other due to defects in the carnitine palmitoyl transferase 2 gene (CPT2)." (PMID 28516087, 2017). "Between attacks patients with CPT2 deficiency generally do not experience symptoms of myopathy, myalgia or muscle weakness, and show no abnormal laboratory findings, including normal serum CK and carnitine levels." (PMID 39473663, 2024). "Regarding patients with CK levels of >10,000 UI/L, one presented DMD, one gamma-sarcoglicanopathy, one CPT2, and one non-classified myopathy." (PMID 39767891, 2024). "Based on this, fluvastatin-induced impairment of CPT2-dependent FAO in the skeletal muscles may lead to elevated FFAs and acylcarnitines, which, in addition to ROS, contribute to activated Pkcdelta-mediated inhibition of skeletal muscle chloride channels and subsequent myopathy-like phenotypes." (PMID 38336990, 2024).
infection (9 papers, 2020 to 2025). The state of being infected such as from the introduction of a foreign agent such as serum, vaccine, antigenic substance or organism. "(A) Seahorse flux analyses of scramble or Plin2-/-, Slc27a1-/-, and Cpt2-/- macrophages infected with Mtb Erdman strain at a multiplicity of infection (MOI) of 1 24 hours post infection." (PMID 40080408, 2025). "On the other hand, we uncovered that the relative abundance of CPT1A and CPT2, which encode Carnitine O-palmitoyltransferase, a rate-limiting enzyme involved in the fatty acid oxidation (FAO), were significantly up-regulated post infection, indicating accelerated FAO pathway." (PMID 37256871, 2023).
genetic diseases (4 papers, 2014 to 2024). "Carnitine palmitoyltransferase II (CPT2) deficiency is a rare genetic disorder that prevents the body from using long-chain fatty acids (LCFAs) for energy." (PMID 39850164, 2024). "These genetic diseases can be caused by mutations in genes such as CPT1, CACT, and CPT2, leading to defective FA oxidation." (PMID 33371457, 2020).
blood disorders (2 papers, 2022 to 2024). "In addition, genes associated with hematological disease (e.g., PDE7A, LMAN1, F13A1, OLR1) and mitochondrial biogenesis and redox (e.g., NOS3, ALDH5A1, PRXL2A, SLC25A13, CPT2) were also significantly altered in BPD patients." (PMID 35484630, 2022).
kidney (2 papers, 2022 to 2024). "Indeed, the expression of Cpt2 is decreased in the results of single cell sequencing, whereas EP4 expression increases in macrophages in response to ischemic kidney injury." (PMID 36467025, 2022).
kidney diseases (2 papers, 2022). "Whereas the role of tubular CPT1A (which encodes a protein located at the outer mitochondrial membrane) in cellular and molecular changes associated with kidney fibrosis has been elucidated, the role of CPT2, which is located in the inner membrane, in kidney diseases remains unclear." (PMID 35998043, 2022).
cardiac disease (1 paper, 2021). "Together, these data suggest that dietary octanoate cannot rescue CPT2-deficient cardiac disease." (PMID 33757734, 2021).
CPT2 also shares sentences with these, for which no sentence is quoted: very-long-chain acyl-CoA dehydrogenase deficiency (6 papers); carnitine deficiency (5); LCHAD deficiency (4); fatty acid metabolism disorders (3); hypermethioninemia (3); methylmalonic acidemia (3); migraine (3); muscular dystrophy (3); trifunctional protein deficiency (3); Alzheimer disease (2); beta-ketothiolase deficiency (2); brain edema (2); Cachexia (2); chronic kidney disease (2); congenital myopathies (2); cystic fibrosis (2); Depression (2); homocystinuria (2); Hyperkalemia (2); muscle disorders (2); nonalcoholic steatohepatitis (2); prostate carcinoma (2); type 2 diabetes (2); urea cycle disorder (2); acute myeloid leukemia (1); acute respiratory failure (1); acute tubular necrosis (1); alcoholic hepatitis (1); amino acid metabolic disease (1); ampullary adenocarcinoma (1).
A further 97 diseases each share a sentence with CPT2 in 1 paper.